HLA-C (major histocompatibility complex, class I, C)
Diseases named in the same sentence as HLA-C in open-access papers (continued):
Sharing a sentence is not in itself a finding about the gene and the disease.
rheumatoid arthritis (40 papers, 2007 to 2025). A chronic, systemic autoimmune disorder characterized by inflammation in the synovial membranes and articular surfaces. "Increased frequency of HLA-C variants in rheumatoid arthritis (RA) is correlated with the strong association between RA and the KIR2DS2 activating receptors." (PMID 36134954, 2022).
glioma (36 papers, 2014 to 2025). A benign or malignant brain and spinal cord tumor that arises from glial cells (astrocytes, oligodendrocytes, ependymal cells). "Another two similar neoepitopes from H3 K27M mutations, MSAPATGGV and MSAPSTGGV, were predicted to bind HLA-B*15:17, HLA-A*68:02, HLA-A*02:05, HLA-C*12:03, or HLA-C*03:04 alleles in nine different high-grade glioma patients." (PMID 28854978, 2017). "High-grade gliomas showed the highest HLA class I expression, with median HLA-A between 8.8 and 9.5 and HLA-C between 7.7 and 8.4 across H3G34-DHG, H3K27M-DMG, H3WT-HGG, and adult HGG, consistent with stronger antigen presentation." (PMID 41312385, 2025). "To confirm the HLA-C expression patterns, we obtained the RNA sequencing data of gliomas from the Human Protein Atlas (HPA) database, which demonstrated that HLA-C was expressed in glioma tissues." (PMID 37762486, 2023). "The fold change of the HLA-C gene was observed to be relatively higher in the plasma samples of glioma patients compared to healthy controls." (PMID 34643804, 2022). "The results of the DEG co-expression network showed that the HLA family (HLA-A, HLA-B, HLA-C, HLA-E, HLA-DRA, HLA-DRB1, and CD74 [HLADG]) plays a vital role in the network, suggesting that tumor immunity is involved in glioma formation." (PMID 34660294, 2021).
HIV-1 infection (35 papers, 2008 to 2026). The type species of lentivirus and the etiologic agent of acquired immunodeficiency syndrome (AIDS). "Our findings demonstrate that the multistep coevolution of HIV-1 with HLA-C-restricted HIV-1-specific T cells is associated with disease progression in HIV-1 infection." (PMID 42022213, 2026). "Recently, attention has been turned to the study of human leukocyte antigen C (HLA-C) genetic variants, which are involved in HIV-1 infection control." (PMID 36499177, 2022). "It has been reported that HLA-C variants that possess higher expression levels were associated with better HIV-1 infection control." (PMID 36499177, 2022). "Different effect of two HLA-C*14 subtype alleles on the epitope-specific T cell responses expanded in HIV-1 infection." (PMID 35475667, 2022). "Most of these studies focused on HLA-A/B alleles, and the role of HLA-C alleles in HIV-1 infection has been less thoroughly explored." (PMID 35475667, 2022). "Early genome-wide association studies identified a strong effect of a variant marking HLA-C in the outcome of HIV-1 infection." (PMID 30180214, 2018). "Our present work underlines the significant role of HLA-C as a key player in the control of HIV-1 infection." (PMID 29070683, 2018). "The protective role of highly expressed HLA-C alleles in HIV-1 infection is in apparent contrast to our previous studies suggesting a role for the HLA-C–Env association in the enhancement of viral infectivity." (PMID 29070683, 2018). "In particular, a single nucleotide polymorphism (SNP) rs9264942, which is 35kb upstream from HLA-C and is associated with expression of HLA-C mRNA, suggested that HLA-C contributes to viral load set point in HIV-1 infection." (PMID 28769934, 2017). "Our study suggests that HLA-C*07:01 is a susceptibility factor in HIV-1 infection." (PMID 39599823, 2024). "Considering that unstable HLA-C variants are associated with worse control of HIV-1 infection, taking the HLA-C genotype into account could contribute to the development of new personalized therapeutic approaches for HIV-1." (PMID 36499177, 2022). "The focus of this work was to determine whether there was an association between HLA-C variants’ stability and HIV-1 infection control." (PMID 36499177, 2022). "The statistical analysis of HLA-C patient’s genotypes classified as homozygous for stable/unstable alleles or heterozygous indicates that there is a strong association between unstable HLA-C genotypes and a worse control of HIV-1 infection (p-value 0.0078)." (PMID 36499177, 2022). "However, a growing body of evidence has recently begun to indicate a protective role for HLA-C alleles in HIV-1 infection." (PMID 31217245, 2019). "HLA-C expression is associated with a differential ability to control HIV-1 infection." (PMID 29070683, 2018). "According to this model, individuals with low-expression HLA-C alleles and unstable binding to β2m/peptide might have worse control of HIV-1 infection and an intrinsically higher capacity to support viral replication." (PMID 29070683, 2018). "Studies addressing the characterization of the HLA-C molecular isoforms on infected cells expressing escape versus deleted alleles are warranted to gain novel insights into the potential protective or pathogenic properties of HLA-C in HIV-1 infection." (PMID 22571741, 2012). "In contrast, the HIV-infected population without ADC showed the same distribution than the general population of northern Italy, thus excluding the hypothesis that the higher frequency of unstable HLA-C alleles is associated with a higher susceptibility to HIV-1 infection." (PMID 30298049, 2018). "In the asymptomatic, antiretroviral drug-untreated phase, individuals with low-expression and unstable HLA-C alleles might have a more rapid disease progression, whereas individuals with highly expressed and stable HLA-C alleles would better control HIV-1 infection." (PMID 29070683, 2018).
HIV-1 infection (continued). "Based on these considerations, HLA-C typing made it possible to calculate a stability score related to each patient’s genotype and to correlate this value to different outcomes of HIV-1 infection." (PMID 41459481, 2025). "HLA-C plays a crucial and multifaceted role in HIV-1 infection, influencing immune recognition, disease progression, and neurocognitive outcomes." (PMID 41459481, 2025). "Recently, HLA-C*03:02 and HLA-C*14 subtypes have the potential to impact viral control in cases of HIV-1 infection." (PMID 40562176, 2025). "In this study, we investigated the impact of KIR/HLA-C interactions on the NK cell repertoire and HIV-1 sequence polymorphisms in the context of HIV-1 infection." (PMID 35911762, 2022). "Together, these studies indicate that HLA-C also plays an important role in control of HIV-1 infection." (PMID 35475667, 2022). "Together, these results suggest that the single substitution at position 21 in these 2 HLA-C*14 subtypes affects the epitope-specific T cell responses expanded during HIV-1 infection." (PMID 35475667, 2022). "In another published work, it has been reported that HLA-C expression levels correlate with a higher cytotoxic T lymphocyte response and with HIV-1 infection control." (PMID 36499177, 2022). "The aim of this work was to examine HLA-C’s impact on HIV-1 infection advancement and progression toward AIDS." (PMID 36499177, 2022). "KIR2DL1-3+ NK cells were more polyfunctional in primary HIV-1 infection in individuals with their cognate HLA-C haplotypes; however, they were disproportionately subject to NK cell dysfunction in the transition to the chronic phase of infection." (PMID 34831331, 2021). "Consistent with emerging evidence, we demonstrate the role of HLA-C in the control of HIV-1 infection in children." (PMID 34512729, 2021). "GWAS comparing HIV controllers and chronically infected individuals with advanced disease progression highlighted the importance of HLA-C in HIV-1 infection." (PMID 34831331, 2021). "We investigated the association of HLA-B, HLA-C, and KIR genotypes with TB, HIV-1 infection, and IRIS onset." (PMID 31959123, 2020). "In contrast to the many studies focusing on HLA-B, relatively few studies have addressed the role of HLA-C in HIV-1 infection." (PMID 31217245, 2019). "Together, these studies indicate that despite being expressed at lower levels than HLA-A or -B, HLA-C plays an important role in HIV-1 infection." (PMID 31217245, 2019). "We thank Dr. A. Beretta for the stimulating discussions on the topic of the interaction between HLA-C, HIV-1 infection, and neurological diseases." (PMID 30298049, 2018). "The correlation between HIV-1 infection and HLA-C free chains expression was also observed in an infection model using a different human T-lymphocytic cell line, PM1, chronically infected with HIV-1 III-B." (PMID 28051183, 2017). "On the other hand, it has been reported that HLA-C is involved in the immune control of HIV-1 infection, contributing to recognition by CTLs and lysis of HIV-infected cells." (PMID 28051183, 2017). "Several evidences of the interaction between Env and HLA-C indicate that the presence of HLA-C is necessary to facilitate HIV-1 infection." (PMID 28051183, 2017). "The strong genetic association between high expression of HLA-C and control of HIV-1 suggests that, at least, in the initial setting of HIV-1 infection, the role of HLA-C in inducing an effective CTL response dominates over other functions of the molecule." (PMID 22571741, 2012). "Assuming that alleles at HLA-C and HLA-A can act in concert to confer genetic advantage during HIV-1 infection (or disadvantage in other settings), differences in peptide-binding and in HLA-C allelic expression can offer two plausible explanations." (PMID 20224785, 2010).
HIV-1 infection (continued). "In line with results previously reported with HIV-1 infection in vitro, endogenously HIV-1 infected CD4+ T cell blasts selectively down-modulated HLA-A and –B alleles while the expression of HLA-C and HLA-E molecules was conserved." (PMID 18617991, 2008). "Despite its historically perceived lower relevance, emerging evidence has demonstrated that HLA-C plays a significant role in modulating immune responses, particularly in HIV-1 infection, influencing viral replication, immune escape mechanisms, and disease progression." (PMID 41459481, 2025). "As such, the molecular and immunological basis of how HLA-C*03:02 confers its protective effects against HIV-1 infection remains unknown." (PMID 39273630, 2024). "As HLA-C is expressed at lower levels on the cell surface than HLA-A or -B (33, –, 35), it was originally assumed that HLA-C may make a less important contribution to control of HIV-1 infection." (PMID 35475667, 2022). "Another element that can influence HIV-1 infection control is HLA-C expression levels." (PMID 36499177, 2022). "Nonetheless, although these studies support the idea that HLA-C-restricted T cells play an important role in clinical outcome of HIV-1 infection, HLA-C remains much less well studied than HLA-A and -B, and the number of HLA-C-restricted HIV-1 epitopes that have been identified is limited." (PMID 35475667, 2022). "Targeting of HLA-A/B and HLA-C by separate viral proteins, and their contrasting patterns of downregulation between individuals, emphasizes differences in the biological role of these HLA molecules in HIV-1 infection." (PMID 30180214, 2018). "The proportion of HLA-C heterotrimers and free chains might play a role in the modulation of HIV-1 infection." (PMID 29070683, 2018). "We reported that HIV-1 infection increases HLA-C free chains on the cell surface." (PMID 29070683, 2018). "This study suggests that HLA-C expression may go beyond its immunological role; rather it could have a deeper implication during HIV-1 infection." (PMID 28051183, 2017). "HIV-1 infection does not directly cause upregulation of HLA-C, neither at the expression level nor by modulating its stability or membrane translocation." (PMID 28051183, 2017). "Overall, the data presented in this work support the hypothesis that HLA-C involvement in HIV-1 infection may confer some advantages to the virus." (PMID 28051183, 2017). "In an interesting parallel, however, the hsa-mir-148a has been proposed to bind HLA-C 3′UTR, and a polymorphism in the binding site for this miRNA, which increase the binding strength, has been associated with poor HIV-1 infection control (see the following section)." (PMID 23841087, 2013). "Identification of one favorable A-C combination (A*30+Cw*03) further supported the role of HLA-C alleles in HIV-1 infection, because none of these alleles individually had a clear association with VL." (PMID 20224785, 2010). "However, there is now increasing evidence to suggest the importance of HLA-C in HIV-1 infection." (PMID 35475667, 2022). "In addition, HLA-B genotypes HLA-B57/B58 or -B27, HLA-B*35:01 and HLA-C, such as the HLA-C*03:02 1 in an African Pediatric Population, are linked with the control of HIV-1 infection (non-progressors bottom box)." (PMID 36140273, 2022). "Altogether, this study demonstrates the significant effects of HIV-1 infection on the NK cell pool in viremic, untreated HIV-1+ individuals and provides evidence that the specific changes in the KIR2DL repertoire are predetermined by the underlying KIR2DL/HLA-C genotypes." (PMID 35911762, 2022). "In addition to HLA-C, there are multiple host and viral factors that may contribute to the control of HIV-1 infection." (PMID 36499177, 2022).
HIV-1 infection (continued). "Our results, reporting for the first time that unstable HLA-C variants are associated with faster AIDS progression, are consistent and support previously published data indicating that unstable/less-expressed HLA-C alleles are correlated to worse control of HIV-1 infection." (PMID 36499177, 2022). "HLA-C expression has been associated with a different ability to control HIV-1 infection, with high HLA-C expression levels associated to a better control of HIV-1 infection, and low HLA-C expression levels associated with poor HIV-1 control and rapid progression to AIDS." (PMID 30298049, 2018). "While HLA-C allotypes also show fairly broad variation in binding scores similar to HLA-B, their lower expression levels may diminish their effect in regulating myelomonocytic cells in HIV-1 infection." (PMID 24603468, 2014). "In recent years multiple studies have drawn attention to the potential role of HLA-C and its cognate inhibitory receptors, KIR2DL1, KIR2DL2, and KIR2DL3, in the intrinsic control of HIV-1 infection." (PMID 35911762, 2022). "Once again, it is emblematic in this regard to observe HIV-1 infection, in which it has been shown that higher levels of HLA-C expression, regardless of specific allotypes, and specific peptides, are associated with better prognosis." (PMID 36325330, 2022). "Accumulating evidence indicated that interactions between HLA-C and its inhibitory KIR2DL receptors (KIR2DL1/L2/L3) can drive HIV-1-mediated immune evasion and thus may contribute to the intrinsic control of HIV-1 infection." (PMID 35911762, 2022). "HLA-C Cw*0602 has not been previously shown to have an independent effect in HIV-1 infection, although the interaction of its gene product with its appropriate cognate KIR molecule most probably plays a role." (PMID 28702030, 2017). "This study suggests that although HIV-1 infection does not upregulate HLA-C expression, HIV-1 envelope may facilitate dissociation of β2M from HLA-C, leading to higher levels of HLA-C free chain molecules at the cell surface influencing HIV-1 infectivity." (PMID 28769934, 2017).
multiple sclerosis (34 papers, 2007 to 2025). A progressive autoimmune disorder affecting the central nervous system resulting in demyelination. "Our analysis indicates that three DRB1 alleles (*1501, *03, and *0103) and one HLA-C allele (*05) exert independent effects on susceptibility to multiple sclerosis." (PMID 17252545, 2007). "Variation in the HLA-C gene influences susceptibility to multiple sclerosis independently of any effect attributable to the nearby HLA-DRB1 gene." (PMID 17252545, 2007). "Using a combination of microsatellite, SNP, and HLA typing in family-based and case–control cohorts from two different populations, we have shown that HLA-C exerts an independent effect on susceptibility to multiple sclerosis above and beyond any effects attributable to the nearby DRB1 gene." (PMID 17252545, 2007). "The SNP rs1049853 in HLA-C was identified in multiple sclerosis patients and was controlled by the miRNA hsa-miR-4428." (PMID 29653596, 2018). "HLA-C was found to be located on chromosome 6 and several previous studies have found the function of HLA-C in multiple sclerosis that was activated by killer cell immunoglobulin like receptor, two Ig domains and long cytoplasmic tail 2(KIR2DL2)." (PMID 29653596, 2018). "Alternately, as the effect appears to be allele rather than functional group specific, it may indicate that susceptibility to multiple sclerosis is conferred by an aspect of HLA-C function that is independent of its interaction with KIR." (PMID 17252545, 2007).